CD38 (CD38 molecule)
Diseases named in the same sentence as CD38 in open-access papers (continued):
Sharing a sentence is not in itself a finding about the gene and the disease.
chronic lymphocytic leukemia (64 papers, 2011 to 2025). "The objective of this study was to evaluate the cluster of differentiation-38 (CD38) expression in Sudanese patients with chronic lymphocytic leukemia (CLL) and to determine its association with clinical and laboratory characteristics of the disease." (PMID 30442182, 2018). "Chronic lymphocytic leukemia with high expression of CD38 confers a less favorable prognosis due to the association of CD38 with migration and homing of CLL cells to secondary lymphoid organs." (PMID 30079267, 2017). "In another gene expression analysis, NCKAP1L was found to be significantly overexpressed in B-cell chronic lymphocytic leukemia (CLL) cells expressing high CD38, a cell marker associated with poor clinical outcome." (PMID 39026677, 2024). "Between 2004 and 2005, studies have primarily focused on CD38 expression, chronic lymphocytic leukemia, acute lymphocytic leukemia and flow cytometry." (PMID 40529366, 2025). "Several studies have documented the progression of CD38-targeting antibodies in other hematologic neoplasms, including chronic lymphocytic leukemia, T-cell acute lymphoblastic leukemia, and natural killer (NK)/T-cell lymphoma." (PMID 40382743, 2025). "CD38+HLA-DR+ mT cell frequencies have been shown to increase in chronic lymphocytic leukemia, gliomas, chronic infections, and immune disorders, where they are typically associated with a worse prognosis." (PMID 40124502, 2025). "This aligns with findings in chronic lymphocytic leukemia, where CD38 expression enhances adhesion and migration in malignant cells, while CD38 blockade inhibits these properties." (PMID 39065794, 2024). "CD20 was included to enable identification of B-lymphocytes in primary samples, and CD38 as a potential surrogate marker for NF-κB activation, as seen in chronic lymphocytic leukemia." (PMID 37333821, 2023). "The relevance of this B cell population has been highlighted using blocking anti-CD38 antibodies in chronic lymphocytic leukaemia (CLL) that targets and depletes both B and T regulatory cells." (PMID 35350071, 2022). "CD38 is also expressed on pathological cells such as chronic lymphocytic leukemia cells, where a presence of a major clone CD38+ positive is correlated with an unfavorable prognosis, and on MM cells." (PMID 34307150, 2021). "In chronic lymphocytic leukemia (CLL), increased CD38 expression is associated with unfavorable prognosis, along with T cell inhibition." (PMID 33936090, 2021). "A previous study demonstrated that the increased Ki-67 expression was found in CD38+ sub-populations from chronic lymphocytic leukemia cells." (PMID 34211854, 2021). "Cox regression analysis was conducted for prediction of LDT within B cell CLL patients, using age, gender, ALC, BM lymphocytes, staging, CD38, and NOTCH1 mutations as covariates." (PMID 32458636, 2020). "Cox regression analysis was conducted for prediction of PFS in B cell CLL patients, using age, gender, ALC, BM lymphocytes, staging, CD38, NOTCH1 mutations as covariates." (PMID 32458636, 2020). "In chronic lymphocytic leukemia (CLL), the pattern of sno/scaRNAs expression is unrelated to the major biological (ZAP-70 and CD38), molecular (immunoglobulin heavy chain gene mutation), and cytogenetic markers." (PMID 32916783, 2020). "The wide expression of CD38 in hematological malignancies, including multiple myeloma (MM), chronic lymphocytic leukemia (CLL), ALL, AML, and NK-cell leukemias, has made this antigen an attractive molecule for immunotherapeutic strategies." (PMID 33081391, 2020). "An increased expression of CD38 is correlated with a poor prognosis in chronic lymphocytic leukemia cells." (PMID 31960110, 2020). "In chronic lymphocytic leukemia, the prognostic significance of CD38 expression is well accepted, and preclinical studies on the use of Daratumumab in monotherapy or combination therapy have demonstrated considerable efficacy." (PMID 32225002, 2020).
chronic lymphocytic leukemia (continued). "Cox regression analysis was conducted for prediction of OS within studied B cell CLL cases, using age, gender, BM lymphocytes, ALC, CD38, staging, NOTCH1 mutations as covariates." (PMID 32458636, 2020). "In chronic lymphocytic leukaemia (CLL) cells, CD44, integrin α4 (also known as CD49d) and pro-MMP-9 are physically linked to CD38 in a supramolecular cell surface complex." (PMID 24713998, 2014). "Using microarray based gene expression profiling we have recently demonstrated that the gene for Pgrn, granulin (GRN), is significantly higher expressed in aggressive CD38+ZAP-70+ as compared to indolent CD38−ZAP-70− chronic lymphocytic leukemia (CLL) cases." (PMID 24009671, 2013). "CD38, ZAP 70, IgHV gene mutational status and cytogenetic changes are proven negatively influence the evolution of chronic lymphocytic leukemia." (PMID 31803286, 2012). "Also, supporting a role for CD38 in chemotaxis, human chronic lymphocytic leukemia (CLL) cells expressing high levels of CD38 exhibit enhanced in vitro migration in response to chemokines." (PMID 33329591, 2020). "Moreover, in B-cell CLL, CD38 is also expressed on CD4+ Tn and Tcm subsets, and the proportion of CD38+ B cells is a predictor of clinical outcome." (PMID 32093678, 2020). "Expression of CD38 on leukemic cells has been associated with poor clinical outcomes in patients with chronic lymphocytic leukemia (CLL) and is considered as the negative predictor of progression." (PMID 32708233, 2020). "CD38 has been identified as a poor prognostic factor for chronic lymphocytic leukemia." (PMID 27391070, 2016). "Besides CML, CD38 expression is used as a prognostic indicator in chronic lymphocytic leukemia (CLL), and CD38 expression is closely related with Ig V gene hypermutation status." (PMID 24967705, 2014). "Samples from patients with B-cell chronic lymphocytic leukemia (B-CLL) and multiple myeloma (MM) were treated ex vivo with the eNK cells, alone and in combination with monoclonal antibodies such as daratumumab (anti-CD38) and/or pembrolizumab (anti-PD1)." (PMID 37686362, 2023). "A general consensus was reached that CD38 expression was a poor prognostic marker for chronic lymphocytic leukemia (CLL)." (PMID 34211854, 2021). "In line with our findings, high CD38 expression levels have also been reported in the CD4+ Tcm cell subset of patients with B cell chronic lymphocytic leukemia (CLL)." (PMID 32093678, 2020). "Analysis of different human leukemias also gave fruitful results, especially in B-cell chronic lymphocytic leukemia (B-CLL).CD38 is a dependable marker for a subset of B-CLL patients and provides differential prognostic information." (PMID 33322499, 2020). "Upregulation of CD38+ on activated CD8+ T cells has been widely used as a prognostic marker for various diseases, including HIV infection and chronic lymphocytic leukemia." (PMID 38680487, 2024). "Enhanced expression of the CD38 membrane protein has also been reported in other aggressive hematological malignancies, including chronic lymphocytic leukemia (CLL), T-cell acute lymphoblastic leukemia (T-ALL), diffuse large B-cell lymphomas (DLBCL), and T and NK lymphomas (NKTL)." (PMID 36139103, 2022). "On the other hand, increased CalDAG-GEFI/Rap1 signaling is responsible for increased cell migration in chronic lymphocytic leukemia (CLL) downstream from acyclic ADP ribose hydrolase, CD38." (PMID 32120817, 2020). "Cortactin is upregulated in several cancers to trigger cell migration and invasiveness, and both cortactin and HS1 are related to poor prognosis in adult B-cell chronic lymphocytic leukemia (B-CLL), and linked to high levels of the known risk factors ZAP70 and CD38." (PMID 30573781, 2019). "FC can also be used to identify the expression of targets for potential antibody-directed therapy and provide additional prognostic information such as CD38 and ZAP-70 expression in chronic lymphocytic leukemia/small lymphocytic lymphoma (CLL/SLL)." (PMID 27725920, 2016).
chronic lymphocytic leukemia (continued). "The role of CD38 has been informative in different pathological disorders, such as in AIDS (where CD38 is one of the earliest indicators of infection) and B cell chronic lymphocytic leukemia (B-CLL)." (PMID 24489445, 2013). "VLA-4 and CD38 predict a poor clinical outcome in chronic lymphocytic leukemia (CLL)." (PMID 21876768, 2011). "Similarly, in chronic lymphocytic leukemia (CLL), CD38, a marker of poor prognosis, increased intracellular Ca2+ concentrations by converting NAD+ to ADPR and cADPR." (PMID 39852780, 2024). "In B‐cell chronic lymphocytic leukaemia (B‐CLL), CD38 expression predicts poor prognosis." (PMID 39364393, 2024). "His medical history included a papillary thyroid cancer treated with radiation therapy 8 years prior, untreated chronic lymphocytic leukemia (Rai stage 0; 13q, CD38, and ZAP-70 negative) 17 years prior, and a current prostate-specific antigen (PSA) value of 9 ng/ml (normal <4 ng/ml)." (PMID 38632333, 2024). "Studies examined biopsies and serum samples from patients with B-cell chronic lymphocytic leukemia (CLL) and found that the levels of IL-9 mRNA and protein expression were altered and correlated with Rai staging, ZAP70, and CD38." (PMID 37048814, 2023). "Chronic lymphocytic leukemia (CLL) is characterized by the accumulation of neoplastic B lymphocytes that escape death, and correlates with the expression of negative prognostic markers such as the CD38 antigen." (PMID 37760777, 2023). "Studies have revealed the importance of CD38 in a range of diseases, e.g. CD38 is a marker of AIDS progression and a negative prognostic marker of chronic lymphocytic leukemia." (PMID 23840430, 2013).
lupus (56 papers, 2008 to 2026). "In models of the autoimmune disease lupus, Cd38 deletion accelerates disease progression, suggesting that CD38 deficiency can exacerbate inflammation." (PMID 41400119, 2026). "This study aimed to elucidate the transcriptomic signatures and dysregulated pathways associated with the autoimmune response in Cd38-/- mice compared to wild-type (WT) mice within the bm12 chronic graft-versus-host disease (cGVHD) lupus model." (PMID 39995666, 2025). "Daratumumab, an anti-CD38 monoclonal antibody shows promise in refractory autoimmune diseases such as systemic lupus erythematosus, Sjögren’s syndrome, and ANCA-associated vasculitis." (PMID 40956308, 2025). "By depleting autoreactive plasma cells, CD38 inhibition reduces pathogenic autoantibody production, making it an attractive therapeutic strategy in systemic lupus erythematosus." (PMID 41373894, 2025). "This is illustrated by the overexpression of CD79a and CD79b, molecules involved in the transduction of BCR signal, and of CD81 whose co-expression with BAFFR and CD38 in transitional B-cells is associated with active systemic lupus erythematosus." (PMID 39185406, 2024). "This aligns with observations in other inflammatory conditions like lupus, where lower IgD + CD38− B cells are associated with reduced disease activity." (PMID 38650858, 2024). "Research in CD38−/− mice found that CD38 deficiency ameliorated the course of pristane-induced lupus." (PMID 33670902, 2021). "Expression of CD38 was closely associated with autoimmunity development, as demonstrated in a mice model of lupus, thus suggesting its immunoregulatory role." (PMID 34681587, 2021). "Our data demonstrate that CD38 promotes pristane-induced chronic inflammation and increases susceptibility to experimental lupus by an apoptosis-driven and Transient Receptor Potential Melastatin 2 (TRPM2)-dependent mechanism." (PMID 30257456, 2018). "In lupus models, this could also be approached by analyzing the functional effect of CD38 deficiency." (PMID 34504495, 2021). "For instance, although CD38 deficiency impairs immune responses and disease pathogenesis in murine arthritis and asthma models, it can instead exacerbate murine models of lupus and diabetes." (PMID 30042766, 2018). "Interestingly, although increased CD38 expression has been identified as one of the biomarkers of Bregs in both humans and mice, the frequency of B10 cells (CD19+CD1dhiCD5+) was found to be significantly higher in CD38 deficient lupus mice, when compared with those wild-type counterparts." (PMID 40458534, 2025). "For example, CD38 deficiency suppressed SLE in the pristane-induced, type I IFN-dependent, murine lupus model." (PMID 33329591, 2020). "In the cGVHD lupus model Art2b, which encodes ART2.2, is upregulated in WT PECs, and to a lesser extent in Cd38-/- PECs." (PMID 39995666, 2025). "In systemic lupus erythematosus, the upregulation of CD38 and HLA-DR on CD4+ and CD8+ T cells signifies a state of chronic immune activation." (PMID 40370439, 2025). "We have previously shown in cGVHD lupus model the failure of host Cd38-/- B cells to fully activate and expand CD38-sufficient donor bm12 T cells." (PMID 39995666, 2025). "CD38 has been found to suppress mitophagy, leading to reduced mitochondrial fitness and weakened cytotoxic responses in lupus patients." (PMID 40491969, 2025). "Researchers also discovered that in individuals with lupus, CD38 expression extends beyond plasma cells to include plasma blasts, mature B cells, and dendritic cells resembling plasma cells." (PMID 38799465, 2024). "cTph↑, CD38+ cTph1↑, and Tph cells were correlated with lupus disease activity index and plasma cells." (PMID 37077922, 2023). "Daratumumab, a monoclonal antibody targeting CD38, induced substantial clinical responses in cases with life-threatening lupus, sustained afterward by maintenance therapy with belimumab." (PMID 37138867, 2023).
lupus (continued). "CD38 can undermine the cytotoxic function of CD8+ T lymphocytes in systemic lupus erythematosus (SLE)." (PMID 36077708, 2022). "Monocyte analysis in patients with systemic lupus erythematosus showed that although all monocytes expressed CD38, high expression of CD38 in atypical monocyte subsets was related to the disease." (PMID 35251964, 2022). "In a previous study using the pristane lupus model, we demonstrated the crucial role for CD38 in promoting aberrant inflammation and lupus-like autoimmunity via an apoptosis-driven mechanism, which requires TRPM2 expression." (PMID 34504495, 2021). "We found that CD38 expression is essential for maintaining the immunoregulatory phenotype and expanding Treg cells from lupus-prone mice." (PMID 34769406, 2021). "Given its uniformly high expression on plasma cells, CD38 has been considered as a therapeutic target in patients with systemic lupus erythematosus (SLE)." (PMID 33670902, 2021). "To evaluate this, we correlated CD38 expression in T-cells with FoxP3 expression and immunosuppressive markers in lupus-prone mice." (PMID 34769406, 2021). "It has been reported that patients with systemic lupus erythematosus (SLE) showed increased CD38+CD25+ T-cells correlating with immune activation and clinical signs." (PMID 34769406, 2021). "Using fluorochrome-conjugated autoantigens, we detected IgG+CD38+ memory B cells with specificity for different autoantigens in mice with lupus by flow cytometry." (PMID 34335611, 2021). "Using the pristane lupus model, we have demonstrated the crucial role of CD38 in promoting aberrant inflammation and lupus-like autoimmunity via an apoptosis-driven mechanism, which requires TRPM2 expression." (PMID 34504495, 2021). "It is unclear what role CD38 plays in CLE pathogenesis, though knocking CD38 out of MRL-lpr mice accelerates lupus." (PMID 32714331, 2020). "Overall, our results imply that CD38 contributes to the development of pristane-induced lupus, particularly during the inflammatory phase prior to the onset of the autoimmune phase of the disease, which occurs 12–16 weeks post treatment." (PMID 29463868, 2018). "In the present study, we examined the role of CD38 during the early inflammatory phase of pristane-induced lupus, a murine model of systemic lupus erythematosus (SLE)." (PMID 29463868, 2018). "The functional ex vivo assays showing increased frequencies of IL-10-producing B cells in Cd38−/− splenocytes than in WT upon stimulation with an agonist anti-CD40 mAb are in agreement with the in vivo experiments in the pristane-induced lupus model." (PMID 30257456, 2018). "Now that our study has highlighted the potential importance of purinergic signaling in lupus, future studies should consider parallel/compensatory pathways such as CD38/CD203a, as well as adenosine deaminase, in both mice and humans." (PMID 29942314, 2018). "Elevated levels of the IgD+CD38+ naive 2 equivalent of pre-germinal center B cells have been reported in the peripheral blood children with systemic lupus erythematosus, but this B cell subset is rarely observed in peripheral blood of healthy individuals." (PMID 19019204, 2008). "As also shown by this study, Rab4A promotes CD38 recycling and surface expression in CD19+ B cells that likely underlie B cell activation, expansion of plasma cells, and enhanced autoantibody production in lupus-prone B6.TC/Rab4AQ72L mice." (PMID 40585226, 2025). "However, despite the limited number of patients in each subgroup, the lupus subgroup reached statistical significance and power (the power for CD38− DN was only 0.78, but all others were >0.8) in its B cell analysis compared with the control group." (PMID 40647710, 2025). "The relevance of these findings to lupus is that abnormal NAD-dependent deacetylation could be reverted pharmacologically or with anti-CD38 therapy." (PMID 39995666, 2025).